EZH2 (enhancer of zeste 2 polycomb repressive complex 2 subunit)
Diseases named in the same sentence as EZH2 in open-access papers (continued):
Sharing a sentence is not in itself a finding about the gene and the disease.
lymph node metastasis (30 papers, 2013 to 2025). "The univariate analysis showed that factors like tumor differentiation, lymph node metastasis, muscle invasion, age, tumor size, and EZH2 levels were risk factors for overall survival rates." (PMID 38476362, 2024). "RT-qPCR results revealed that low circGSK3B and high EZH2 expression were associated with tumor size (P = 0.018 and P = 0.018, respectively), lymph node metastasis (P = 0.029, P = 0.006) and TNM stage (P = 0.031, P = 0.007)." (PMID 34666800, 2021). "Expression of EZH2 is associated with lymph node metastasis (p = 0.0073) and recurrent (p = 0.0302)." (PMID 31718595, 2019). "Therefore, high expression levels of EZH2 were associated with the pathological grade of tumors and lymph node metastasis." (PMID 35208478, 2022). "Furthermore, we found that higher expression of EZH2 was linked to lymph node metastasis and recurrent." (PMID 31718595, 2019). "Moreover, considering the lymph node status of patients who underwent RC, the rate of lymph node metastasis was associated with significantly increased EZH2 staining compared with non-lymph node metastasis (Mann-Whitney test, p = 0.018)." (PMID 30542123, 2018). "Additionally, Ezh2 expression level was closely associated with lymph node metastasis (P=0.0124)." (PMID 27015363, 2016). "In this study, we found that serum EZH2 levels were significantly associated with factors including TNM stage, tumor size, muscle invasion, and lymph node metastasis." (PMID 38476362, 2024). "High expressed-EZH2 cases more frequently had an advanced clinical stage (lymph node metastasis) and aggressive features than EZH2-low cases, potentially indicating the high risk of HER2-positive BC (p < 0.05)." (PMID 37803297, 2023). "Out of the 21 cases with lymph node metastasis, high EZH2 immunoexpression was found in 20 (20/21, 95.23%) cases and low immunoexpression in only one case (1/21, 4.7%)." (PMID 37131568, 2023). "Clinical and preclinical studies showed an inverse correlation between EZH2 expression and E-cadherin in PDAC, where high EZH2 expression was associated with advanced disease stage and lymph node metastasis." (PMID 36497404, 2022). "In another study of 46 patients with locoregionally advanced SCCHN, EZH2 protein overexpression was determined as an independent predictor of overall survival and outperformed lymph node metastasis, a known prognostic factor in SCCHN." (PMID 33050946, 2020). "Both EZH2 and NSD2 expression were associated with pathological grade of tumor and lymph node metastasis." (PMID 33665162, 2020). "COX regression model analysis showed that high EZH2 expression and lymph node metastasis were correlated with overall survival (OS) (HR = 2.2041, P = 0.011)." (PMID 26848980, 2016). "Univariate analysis identified EZH2 expression, age, T stage, lymph node metastasis, distant metastasis, TNM classification, and tumor recurrence as independent prognostic factors of OS in patients with LUAD (log-rank test, P = 0.041, 0.026, < 0.01, < 0.01, 0.038, < 0.01, and < 0.01, respectively)." (PMID 33276757, 2020). "However, in the present study, our results suggested that increased expression of EZH2 was significantly correlated with more aggressive biological behaviour including higher grade, stage and lymph node metastasis." (PMID 30542123, 2018). "The findings revealed that EZH2 levels were significantly correlated with clinicopathological characteristics including TNM stage, lymph node metastasis, muscle invasion, and tumor size." (PMID 38476362, 2024). "Serum EZH2 levels exhibited a significant correlation with TNM stage, lymph node metastasis, muscle invasion, and tumor size." (PMID 38476362, 2024). "Both EZH2 and NSD2 expression strongly correlated with histological grade of tumor and lymph node metastasis." (PMID 33665162, 2020).
lymph node metastasis (continued). "Both EZH2 and NSD2 protein expression correlated with pathological grade of tumor and lymph node metastasis; the high grade and positive lymph node involvement were associated with increased rate of positive EZH2 and NSD2 (P < 0.001, P = 0.003)." (PMID 33665162, 2020). "Our results showed that the high expression of EZH2 correlated with undifferentiation, high CEA level, T4 status and lymph node metastasis status at diagnosis." (PMID 25159232, 2014). "Our study’s results differ from those of a previous meta-analysis, which suggested that EZH2 expression was significantly associated with TNM stage (n = 9) and lymph node metastasis (n = 7), but not with T status (n = 5) in Asia." (PMID 25974088, 2015). "Using immunostaining, several studies could display an upregulated expression pattern of EZH2 in BTC patients linked with a poor overall survival, larger tumor size and lymph node metastasis compared to patients with no or a low EZH2 expression." (PMID 32331331, 2020). "The study evaluated various methods for EZH2 expression in lip and ear squamous cell carcinomas (LSCC, ESCC) by matching patients with and without lymph node metastasis (LNM) and further analysis of clinical outcome parameters." (PMID 40135141, 2024).
mesothelioma (30 papers, 2016 to 2026). A usually malignant and aggressive neoplasm of the mesothelium which is often associated with exposure to asbestos. "Several preclinical studies showed increased sensitivity to EZH2 inhibition in BAP1-deficient models compared to wild-type mesothelioma." (PMID 40361508, 2025). "This disruption suggests that mesotheliomas with BAP1 mutations are sensitive to inhibitors targeting EZH2, a component of the PRC2 complex." (PMID 40362535, 2025). "It has previously been established that inhibition of EZH2 is therapeutically effective in BAP1-deficient mesothelioma in preclinical settings." (PMID 38054839, 2024). "Our extensive testing in preclinical models of BAP1-deficient mesothelioma show that inhibiting ATM in combination with EZH2 is highly synergistic, showing the potential therapeutic application of this combination." (PMID 38519707, 2024). "A phase 2 trial including 74 patients with BAP1 deficient mesothelioma treated patients with PeM with the EZH2 inhibitor tazemetostat as a monotherapy." (PMID 38642130, 2024). "We demonstrated the efficacy of the combination of ATM and EZH2 inhibition against BAP1-deficient mesothelioma in preclinical models, indicating the potential of this combination as a novel treatment modality using BAP1 as a biomarker." (PMID 38519707, 2024). "We observe that BAP1-deficient human mesothelioma cell lines (except H28) are hypersensitive to the combined treatment of EZH2 inhibitor GSK126 and mevalonate pathway inhibitor ZA." (PMID 36657447, 2023). "show that the combined targeting of mevalonate pathway and EZH2 inhibition effectively kills tumor cells and prolongs the survival of Bap1-deficient mice with mesothelioma." (PMID 36657447, 2023). "Our work revealed that the increased expression of EZH2 was linked to poor OS among Mesothelioma patients." (PMID 36195655, 2022). "Both univariate and multivariate analyses indicated the association of high expression of EZH2 with poor prognosis in mesothelioma patients." (PMID 36195655, 2022). "It has been recently reported that mesothelioma cells that lack BAP1 (BRCA1 Associated Protein) are sensitive to inhibition of the EZH2 (Enhancer of Zeste Homolog 2) histone methyltransferase." (PMID 34277422, 2021). "Also, preclinical reports by us and others have shown that inhibition of EZH2 is therapeutically effective against BAP1-deficient mesothelioma." (PMID 38054839, 2024). "Notably, performing gene set enrichment analysis (GSEA) for hallmarks gene sets on our data shows a clear enrichment of the cholesterol homeostasis pathway due to EZH2 inhibition in the BAP1-deficient H2731 mesothelioma cell line." (PMID 36657447, 2023). "Univariate correlation analysis showed significant association of EZH2 expression with OS (P < 0.001), and the pathological type (HR = 5.96, 95% CI 0.55–64.67, P = 0.020) and EZH2 expression (HR = 2.35, 95% CI 1.62–3.42, P < 0.001) were significantly associated with OS in mesothelioma patients." (PMID 36195655, 2022). "Researchers started a phase II trial to evaluate the impact of tazemetostat, an EZH2 inhibitor, in relapsed PM patients with inactivated BAP1 since mesothelioma cells with inactivated BAP1 are susceptible to EZH2 pharmacologic inhibition." (PMID 40227645, 2025). "A phase II clinical trial has yielded promising results for tazemetostat, an EZH2 inhibitor, in mesothelioma patients with BAP1 inactivation, offering hope for targeted therapies in this patient subgroup." (PMID 40362535, 2025). "A human and murine preclinical model for mesothelioma and uveal melanoma evaluated the efficacy of the synergistic potential of combining inhibition of EZH2 and FGFR." (PMID 40361508, 2025). "A focused drug synergy screen consisting of 20 drugs was performed by combining EZH2 inhibition with a panel of anti-cancer compounds in mesothelioma cell lines." (PMID 38519707, 2024).
mesothelioma (continued). "In summary, we demonstrate that the simultaneous inhibition of EZH2 and ATM is a highly synergistic regimen against preclinical models of BAP1-deficient mesothelioma." (PMID 38519707, 2024). "Using these mouse mesothelioma cell lines, we performed a 72h viability screen using 20 drugs and the EZH2 inhibitor GSK126 as anchor drug." (PMID 38519707, 2024). "Taken together, we were able to show that a combination of FGFR and EZH2 inhibitors is a potentially promising therapeutic strategy for the treatment of BAP1-mutant mesothelioma cells." (PMID 38054839, 2024). "Overexpressed EZH2 was associated with unfavorable OS of patients with adrenocortical carcinoma (ACC), kidney renal clear cell carcinoma (KIRC), LGG, LIHC, mesothelioma (MESO), pheochromocytoma and paraganglioma (PCPG), and PRAD." (PMID 36545914, 2023). "In mesothelioma, BAP1 loss promotes EZH2 expression, but the opposite association was seen in our data (i.e., BAP1 loss was significantly associated with <80% EZH2 expression)." (PMID 37190202, 2023). "In general, and after reviewing various evidence that showed a contrast in the use of EZH2 inhibitors in cancers, especially mesothelioma, it seems that testing the response to EZH2 should be carefully evaluated before using these molecules as therapy." (PMID 36844227, 2023). "Further, we validated these observations in two additional BAP1-negative mesothelioma cell lines and consistently observed that genes belonging to cholesterol metabolism are upregulated upon treatment with an EZH2 inhibitor." (PMID 36657447, 2023). "Previously, we and others have shown that EZH2 inhibition is effective in BAP1-deleted mesothelioma." (PMID 36657447, 2023). "Based on this, we carried out the correlation between EZH2 mRNA levels and the prognosis of mesothelioma patients and immune infiltration analysis depending on the TCGA database." (PMID 36195655, 2022). "While the monotherapy as an EZH2 inhibitor showed robust antitumor activity in the treatment of anti-mesothelioma, with good safety/tolerability." (PMID 36195655, 2022). "High expression of EZH2 predicts a poor prognosis in mesothelioma or can serve as a prognostic indicator and target gene in mesothelioma." (PMID 36195655, 2022). "This study aims to investigate the prognostic value of enhancer homolog 2 (EZH2) mRNA expression in mesothelioma patients accompanied with its immune infiltration analysis." (PMID 36195655, 2022). "Cox analysis was chosen to explore the relationship between EZH2 expression and OS as well as other multivariate characteristics in mesothelioma patients." (PMID 36195655, 2022). "EZH2, as a new prognostic biomarker for mesothelioma, contributes to elucidating how changes in the immune environment promote the development of mesothelioma." (PMID 36195655, 2022). "The presented work here provides a detailed analysis of the role of EZH2 in Mesothelioma development and indicates mesothelioma prognosis, which contributes to the understanding of the underlying mechanisms of Mesothelioma." (PMID 36195655, 2022). "We investigated the correlation between EZH2 expression and the level of immune infiltration in mesothelioma tissues." (PMID 36195655, 2022). "Enhancer of zeste homolog 2 (EZH2) is upregulated in mesothelioma, and preclinical models have identified a possible association between BAP1 loss and EZH2 upregulation." (PMID 33802313, 2021). "In this regard, a recent study has shown that while macrophages can be directly cytotoxic for mesothelioma cells, inhibition of EZH2 reduced that activity because it induced PD-1 overexpression." (PMID 33952230, 2021). "For example, in a mesothelioma model, EZH2 regulated macrophage-induced oxeiptosis of mesothelioma cells, and its blocking impaired macrophage function and tumor control." (PMID 33859645, 2021).
mesothelioma (continued). "This possibility is further supported by the recently reported inverse correlation between strong EZH2 expression and the loss of the chromatin modifier BAP-1, whose increasingly deregulated nature in sporadic mesotheliomas we are currently investigating." (PMID 27705913, 2016). "Given preclinical data demonstrating the antitumor activity of EZH2 inhibition in BAP1 mutant mesothelioma, a phase 2 clinical trial evaluated the safety and efficacy of tazemetostat, a selective oral EZH2 inhibitor, in patients with relapsed or refractory MPM (NCT02860286)." (PMID 38610930, 2024). "In addition to the high sensitivity of BAP1-mutant mesothelioma, we show that the treatment of EZH2 inhibitor in conjunction with FGFR inhibitor is effective in uveal melanoma as well." (PMID 38054839, 2024). "In view of the clinical availability of the inhibitors used against EZH2 (tazemetostat) and FGFR (AZD4547), this highly synergistic combination is worth testing as a therapeutic regimen against mesothelioma and potentially other BAP1-mutated malignancies as well." (PMID 38054839, 2024). "In addition, the combined targeting of EZH2 and an enzyme upstream in the mevalonate pathway, i.e., HMG-coenzyme A (CoA) by lovastatin, also results in reduced survival of BAP1-deficient mesothelioma cells." (PMID 36657447, 2023). "Therefore, we analyzed the correlation of EZH2 expression with the level of immune infiltration in mesothelioma tissues using TIMER." (PMID 36195655, 2022). "In order to explore the relationship between EZH2 and tumor immune microenvironment, we analyzed the correlation of EZH2 expression in mesothelioma tissues with immune infiltration level using TIMER, demonstrating the crucial role of EZH2 expression in immune infiltration." (PMID 36195655, 2022). "The increasing attention to the expression of EZH2 and the immune microenvironment in mesothelioma may significantly contribute to enhancing prognosis, which is worthy of further exploration." (PMID 36195655, 2022). "Our results indicated that EZH2 was closely related to the survival of mesothelioma patients." (PMID 36195655, 2022). "Moreover, mesothelioma patients with high EZH2 expression differ from those with low EZH2 expression in their tumor immune microenvironment." (PMID 36195655, 2022). "Since we observed strong H3K27me3 (histone H3 lysine 27 trimetylation) immunoreactivity in BAP1 wild-type mesothelioma biopsies, we decided to characterize in vitro the response/resistance of BAP1 wild-type mesothelioma cells to the EZH2 selective inhibitor, EPZ-6438." (PMID 34277422, 2021). "Future research should focus on translating EZH2 inhibition into clinical benefit, identifying predictive biomarkers of response, and exploring rational combinations with chemotherapy, targeted drugs, or immunotherapy to improve survival outcomes in mesothelioma patients." (PMID 42257802, 2026). "However, results from mesothelioma mouse models show that EZH2 inhibition alone may show limited efficacy." (PMID 38519707, 2024). "Indeed, our data suggest that some mesothelioma tumors may acquire a CIMP-high phenotype through the activity of the ERG EZH2, to hypermethylate and silence specific target genes." (PMID 36928603, 2023). "The multivariate Cox regression forest plot was drawn according to the results of multivariate analysis, from which it could be concluded that EZH2 expression acted as an independent prognostic factor for the survival of mesothelioma patients (HR = 2.63, 95% CI 1.02–6.79, P = 0.046)." (PMID 36195655, 2022). "Further analysis, EZH2 may serve as a biological test to predict the prognosis of mesothelioma." (PMID 36195655, 2022). "EZH2 and Embryonic Ectoderm Development (EED) encoding polycomb repression complex-2 (PRC-2) have been demonstrated to be overexpressed in MPM lines, occupying about 85% of Mesothelioma in comparison with normal pleura, which is related to the reduced survival rate of patients." (PMID 36195655, 2022).